DMD (dystrophin)
Diseases named in the same sentence as DMD in open-access papers (continued):
Sharing a sentence is not in itself a finding about the gene and the disease.
sarcoma (continued). "Because DMD deletion is thought to occur specifically in sarcomas with myogenic differentiation including leiomyosarcomas (LMS), we looked at the localization of the different isoforms of DMD in LMSs." (PMID 32438562, 2020). "Indeed, DMD-deleted sarcomas could arise from multipotent mesenchymal or muscle-derived stem cells." (PMID 31266185, 2019). "Functionally, previous studies in sarcoma and HNSCC cell models have shown that Dp71ab overexpression leads to reduced proliferation, aligning with our proposed tumour‐suppressive role for DMD in aggressive sarcomas and HNSCC." (PMID 40832923, 2026). "Sarcoma and HNSCC are indeed highly aggressive and metastatic cancers with early and frequent distant spread supporting their categorisation into our more aggressive/DMD suppressive group." (PMID 40832923, 2026). "In contrast, DMD deletions were not seen in 58 non-myogenic sarcomas and were only reported in 4.3% of non-sarcoma human cancer cell lines in the Cancer Cell Line Encyclopedia28." (PMID 30575736, 2018). "DMD deletions were also more frequent in myogenic sarcomas compared to non-myogenic sarcomas (25/40 vs 0/58, respectively) and non-sarcoma tumors (25/40 vs 39/866)." (PMID 27391342, 2017). "Although DMD is the largest gene in the human genome and is part of known fragile site FRAXC, this suggests homozygous deletions of DMD may play a role in sarcoma." (PMID 29089486, 2017). "Moreover, mice lacking the expression of full-length dystrophin (Dmdmdx) have been found be prone to spontaneously develop age-related muscle-derived malignant sarcomas." (PMID 35790299, 2022). "Additionally, sarcoma (which has high genomic instability) and head and neck cancer are also amongst the tumours with the highest number of DMD alterations and HNSCC appears amongst the lists of tumours where DMD expression is significantly downregulated compared to control tissue." (PMID 40832923, 2026). "Indeed, dystrophin has known oncosuppressor functions, although not completely explored, as recently pinpointed for its role in keeping genome stability via, at least in part, ROS release and its capacity to inhibit myogenic cell migration in sarcoma." (PMID 32719714, 2020). "For clarification, RNA-seq data for control tissues for sarcomas was not available in the TCGA TARGET GTEx cohort, and therefore DMD gene expression in sarcomas vs. control tissues could not be compared." (PMID 36900171, 2023).
limb-girdle muscular dystrophy (18 papers, 2009 to 2026). Limb-girdle muscular dystrophy (LGMD) is a heterogeneous group of muscular dystrophies characterized by proximal weakness affecting the pelvic and shoulder girdles. "Sarcoglycans (SGs), β, δ, γ, and α subunits of the dystrophin-glycoprotein complex (DGC), contain essential N-linked glycosylation sites, and mutations disrupt glycan attachment, destabilize the complex, and cause limb-girdle muscular dystrophy." (PMID 42021484, 2026). "In people, the most common forms include the X-linked Duchenne and Becker muscular dystrophies associated with mutations in the dystrophin gene (DMD), and the limb-girdle muscular dystrophies (LGMD) associated with autosomal dominant (LGMD1) or autosomal recessive (LGMD2) mutations in several genes." (PMID 33407862, 2021). "In the subjects with CK ≥ 2000 U/l without DMD mutations, the most common limb-girdle muscular dystrophy (LGMD) genes were investigated and mutations in DYSF, SGCB and FKRP genes were found." (PMID 32112218, 2020).
X-linked recessive disease (18 papers, 2007 to 2024). X-linked recessive form of disease. "DMD is an X-linked recessive disease caused by mutations in the dystrophin gene, disrupting protein production." (PMID 38891777, 2024). "DMD is a X-linked recessive disease caused by a mutation in the dystrophin gene, that, in most cases, leads to its absence in the DGC of striated muscle cells." (PMID 37362434, 2023). "DMD, an inherited X-linked recessive disease caused by more than 7000 patient-specific mutations in the DMD gene, resulting in the lack of dystrophin, a structural protein of muscle cells, is still incurable (for references, see:)." (PMID 36918494, 2023). "DMD/BMD is an X-linked recessive disease caused by sequence alterations occurring in the DMD gene (OMIM *300377) encoding the dystrophin protein." (PMID 34679607, 2021). "This is a genetic X-linked recessive disease caused by mutations in the DMD gene that encode the cytoskeletal protein dystrophin." (PMID 32899500, 2020). "It is a lethal X-linked recessive disease caused by mutations in dystrophin gene (DMD) (HGNC ID: 2928)." (PMID 32430065, 2020). "DMD is an X-linked recessive disease caused by mutations in the dystrophin protein." (PMID 34424816, 2021). "DMD is an X-linked recessive disease, caused by mutations in the dystrophin gene (DMD)." (PMID 30794581, 2019). "DMD and BMD are X-linked recessive diseases caused by the mutations in the DMD gene (Xp21) and the consequent loss of dystrophin protein." (PMID 33339321, 2020). "It is an X-linked recessive disease caused by mutations in the DMD gene which leads to the absence of dystrophin." (PMID 37705069, 2023). "Duchenne musclar dystrophy (DMD) is an X-linked recessive disease caused by mutations of dystrophin gene, there is no effective treatment for this disorder at present." (PMID 17617925, 2007). "DMD is an X-linked recessive disease resulting from a complete absence of the dystrophin protein." (PMID 37362434, 2023).
X-linked dilated cardiomyopathy (16 papers, 2009 to 2025). "The DMD gene is associated with X-linked neuromuscular disorders Duchenne and Becker dystrophies, X linked dilated cardiomyopathy 3B, and familial cardiomyopathy." (PMID 33829027, 2021). "Genetic mutations in a vital muscle protein dystrophin trigger X-linked dilated cardiomyopathy (XLDCM)." (PMID 25340340, 2014). "In X-linked dilated cardiomyopathy due to dystrophin mutations which abolish the expression of the M isoform (5'-XLDC), the skeletal muscle is spared through the up-regulation of the Brain (B) isoform, a compensatory mechanism that does not appear to occur in the heart of affected individuals." (PMID 22455600, 2012). "Besides these phenotypes, X-linked dilated cardiomyopathy is also caused by DMD mutations." (PMID 38288333, 2023). "In contrast, X-Linked Dilated Cardiomyopathy (XLDC, OMIM 302045) due to dystrophin gene mutations is characterized by selective cardiac disease with no significant skeletal muscle symptoms." (PMID 22455600, 2012). "Certain DMD mutations are linked to X-linked dilated cardiomyopathy with absent or subclinical skeletal muscle involvement." (PMID 41204571, 2025).
Arrhythmia (14 papers, 2011 to 2026). Any cardiac rhythm other than the normal sinus rhythm. "This underscores that high dystrophin‐positive cell proportions are crucial to minimize dysfunction and arrhythmia risk." (PMID 41498377, 2026). "Significantly reduced peak INa, a characteristic feature of dystrophin-deficient ventricular cardiomyocytes, represents a relevant source of cardiac arrhythmias." (PMID 38099845, 2024). "Hence, a fundamental unresolved question is at what age the presence of the dystrophin mutation is translated into/manifested as the diverse pathologies, such as bioenergetic deficits and cardiac arrhythmias." (PMID 36077200, 2022). "Finally, it should also be mentioned that abnormal Ca2+ transients in dystrophin-deficient cardiomyocytes predispose the dystrophic heart to cardiac arrhythmias." (PMID 33619211, 2021). "In support of the hypothesis that dystrophin‐mutated iPSC‐CMs from the mutant male and the heterozygous female carrier exhibit key features of DMD, mutated cardiomyocytes displayed molecular, genetic and electrophysiological abnormalities, including arrhythmias." (PMID 30618214, 2019). "DMD female and male iPSC‐CMs presented oscillatory depolarization in 52% and 17% of spontaneous recordings, respectively, while control iPSC‐CMs had no arrhythmias." (PMID 30618214, 2019).
muscle degeneration (14 papers, 2011 to 2025). "In conclusion, the main molecular actors of mitochondrial dynamics, namely DRP-1, EAT-3 and FZO-1, appear to be implicated in the establishment of dystrophin-dependent muscle degeneration." (PMID 29743663, 2018). "Patients with mutations in the DMD gene that result in the loss of the large dystrophin protein isoform (Dp427) show loss of ambulation, severe muscle degeneration, and heart disease." (PMID 27547731, 2015). "Surprisingly, however, PGC-1β transgenesis protects as efficaciously as PGC-1α against muscle degeneration in dystrophin-deficient (mdx) mice, suggesting that alternate mechanisms of protection exist." (PMID 24447845, 2014). "Muscle degeneration in DMD occurs due to mutations in or a loss of dystrophin from the sarcolemmal glycoprotein membrane complex, and results in muscle fragility, contraction-induced damage, necrosis, and inflammation." (PMID 21639930, 2011). "The disease is characterized by progressive skeletal muscle degeneration that arises due to mutations in or loss of dystrophin from the dystrophin-glycoprotein complex (DGC) within the sarcolemmal membrane." (PMID 21639930, 2011). "Although the DMD-XKOXWT females in animal models have been reported to exhibit muscle degeneration, dissimilar pathological features to humans hinder the utility of these animals as faithful models for DMD carriers." (PMID 37772130, 2023). "Collectively, it clearly appears that interfering with the mitochondrial dynamic balance can greatly impact dystrophin-dependent muscle degeneration in C. elegans." (PMID 29743663, 2018). "Collectively, our data converge toward a mechanism that underlies DRP-1-dependent mitochondrial pathways activated downstream of CED-3 to impact dystrophin-dependent muscle degeneration." (PMID 29743663, 2018). "The effects of ced-3 RNAi and of the drp-1(tm1108) mutation on muscle cells of dys-1(cx18);hlh-1(cc561ts) were cumulative indicating that CED-3 probably has an additional role in dystrophin-dependent muscle degeneration, which is DRP-1-independent." (PMID 29743663, 2018). "Here we report a role for DRP-1 in regulating apoptosis induced by dystrophin-dependent muscle degeneration." (PMID 29743663, 2018). "In conclusion, our findings point to mitochondrial dynamics as an early signaling hub that controls cell death in dystrophin-dependent muscle degeneration." (PMID 29743663, 2018). "Previously, DYSTROPHIN had been known as an important ‘linkage’ protein connecting skeletal muscle fibers of cytoskeleton to the extracellular matrix, and DYSTROPHIN’s functional failure results in severe skeletal muscle degeneration, which is the etiology of DMD." (PMID 32011235, 2020). "Then, we wondered whether DRP-1 was required for CED-3 and others cell death executors to impact dystrophin-dependent muscle degeneration." (PMID 29743663, 2018).
Myocardial fibrosis (14 papers, 2011 to 2026). "The presence of LGE in BMD patients is caused by progressive myocardial fibrosis as a consequence of ongoing cardiomyocyte cell death due to genetic dystrophin-deficiency." (PMID 35174232, 2022). "We here demonstrate that dystrophin deficiency in mice leads to cardiac electrophysiological abnormalities from a young age onwards, prior to the development of myocardial fibrosis." (PMID 33963238, 2021). "Myocardial fibrosis was more frequent in carriers of pathogenic variants associated with DMD vs. BMD (61 vs. 28%, p = 0.02)." (PMID 34385974, 2021). "On using CMR, a substantial proportion of the DMD-carriers examined displayed signs of myocardial fibrosis which is associated with clinical parameters." (PMID 27660108, 2016). "Moreover, LGE in DMD/BMD patients is caused by progressive myocardial fibrosis as a consequence of ongoing cardiomyocyte cell death due to dystrophin-deficiency." (PMID 25315351, 2014). "In boys with DMD, dystrophin mutation dictates eventual LV dysfunction and once systolic dysfunction and myocardial fibrosis develop, clinical disease typically progresses very rapidly and long-term survival (as seen in adult patients with LV systolic dysfunction) is poor." (PMID 22011358, 2011). "The associated mechanical stress on the heart during exercise due to pressure and volume overload could hypothetically be harmful to dystrophin-deficient myocardial cells, producing a continuous damage and repair cycle which lead to myocardial fibrosis and ventricular dilation." (PMID 35549971, 2022). "The frequency of myocardial fibrosis in the whole cohort (49%), and of women carrying DMD variants that predict DMD (61%) and BMD (28%), agrees with findings in other studies (DMD 35–65%, BMD 19–20%)." (PMID 34385974, 2021). "Myocardial fibrosis by late gadolinium enhancement was detected in 35% to 65% of DMD carriers." (PMID 39075955, 2024). "One might speculate that: (i) in general, DMD carriers may display diffusely of focally distributed myocardial fibrosis; or (ii) LGE is an advanced form of initially diffuse fibrosis." (PMID 27660108, 2016). "There was an increase in the degree of myocardial fibrosis, but the proportion of dystrophin-negative cardiomyocytes remained almost constant in biopsies performed later at 35 and 44 years of age." (PMID 39075955, 2024). "Hence, micro-dystrophin replacement therapy seems to halt the progression of myocardial fibrosis in a severe model of DMD without fully correcting it compared with a physiological condition." (PMID 40562489, 2025).
spinal muscular atrophy (12 papers, 2013 to 2025). A motor neuron disease that affect the muscles, and characterized by muscle weakness and atrophy resulting from progressive degeneration and irreversible loss of the anterior horn cells in the spinal cord (i.e., lower motor neurons) and the brain stem nuclei. "Use of another naturally occurring sequence, the DG9, a cell-penetrating peptide derived from human polyhomeotic 1 homolog (Hph-1) transcription factor, class of CPP, to improve delivery of PMOs against DMD and spinal muscular atrophy (SMA) targets, has been reported." (PMID 40917895, 2025). "Spinal muscular atrophy and DMD drugs may cease to be the dominant gene and RNA therapies in Medicaid in the future as the number of other available therapies continues to increase." (PMID 38770270, 2024).
Anxiety (11 papers, 2012 to 2025). Intense feelings of nervousness, tension, or panic often arise in response to interpersonal stresses. "Overall, dystrophin deficiency leads to fear and anxiety, impairments in learning and memory, and disturbances in emotional, depression-related and social behaviour." (PMID 40747772, 2025). "These relationships were strongest for Dp140 deficient DMD participants, most likely reflecting the higher anxiety scores in this subgroup." (PMID 35136951, 2023). "This study describes the neuromotor, anxiety and anhedonia characterization of the recently described dystrophin deficient rat model, Dmdmdx rats." (PMID 32160266, 2020). "In order to evaluate the impact of dystrophin loss on behavior, we explored locomotion parameters as well as anhedonia, anxiety and response to stress, in Dmdmdx rats aged from 1.5 to 7 months, in comparison to wild-type (WT) littermates." (PMID 32160266, 2020). "Although at first our proband was reluctant at the possibility of causing anxiety in other healthy relatives, he decided to contact them and several key members agreed to have their DNA screened for mutations in the dystrophin gene." (PMID 22707356, 2012). "We thus demonstrate that anxiety, fear-related behaviors and fear conditioning performance constitute a set of relevant outcome measures in the evaluation of novel therapies aimed at alleviating CNS comorbidities associated with loss of dystrophin isoforms in the brain." (PMID 39718030, 2024). "Overall, it seems that each of the brain dystrophin isoforms has, to a varying degree, a role in anxiety." (PMID 39885828, 2025). "The participation of mdx52 and DMD-null mice was noticeably lower during the first reversal day, indicative of a lower engagement overall, which could result from anxiety." (PMID 39885828, 2025). "We cannot rule out that altered visual processing could have influenced the behavior of mdx52 and/or DMD-null mice in these anxiety tests." (PMID 39885828, 2025). "Interestingly, DMD-null mice were more anxious than mice of the other DMD strains, indicating a prominent role of Dp71 and/or Dp40 in anxiety, which has been indicated before in Dp71-null mice, as they are more anxious than WTs." (PMID 39885828, 2025). "We showed that dystrophin-deficient Dmdmdx rats displayed motor deficits in the beam test, without association with depressive or anxiety-like phenotype." (PMID 32160266, 2020). "This anxious behaviour is even further enhanced in DMD-null mice and, to some extent, in Dp71-null mice, indicating worsening of anxiety with the lack of each brain-related dystrophin isoform." (PMID 40747772, 2025). "Furthermore, the DMD subgroup lacking the Dp140 dystrophin isoform (Dp140−) had higher anxiety scores than the normal population, whilst the subgroup retaining the Dp140 isoform (Dp140+) did not." (PMID 35136951, 2023). "Therefore, the increased risk of ADHD, ASD, anxiety, and OCD in boys with DMD may be related to the lack of dystrophin expression in the brain or to the effect of dystrophin on other central nervous system proteins." (PMID 40722287, 2025). "Furthermore, a similar increase in anxiety levels has only been demonstrated in more severe mouse models of DMD where both Dp427 and Dp140 dystrophin isoforms are missing, unlike the mdx mouse employed here which only lacks Dp427 (full-length dystrophin)." (PMID 40463956, 2025).